SYNGR2 (synaptogyrin 2)
Description:
May play a role in regulated exocytosis. In neuronal cells, modulates the localization of synaptophysin/SYP into synaptic-like microvesicles and may therefore play a role in the formation and/or the maturation of this vesicles. May also play a role in GLUT4 storage and transport to the plasma membrane. (Microbial infection) May play a role in the assembly of cytoplasmic inclusion bodies required for SFTS phlebovirus replication.
Tractability: Antibody: UniProt predicts a signal peptide or a membrane-spanning region. PROTAC: ubiquitination databases record sites on it; its protein half-life has been measured.
Gene: Protein-coding gene on chromosome 17 (78,168,567 to 78,173,527, forward strand). Ensembl gene ENSG00000108639.
Subcellular location: Cytoplasmic vesicle membrane; Cytoplasmic vesicle, secretory vesicle, synaptic vesicle membrane; Lipid droplet
Subcellular location (Human Protein Atlas): Golgi apparatus
Gene Ontology:
Molecular function: protein binding
Biological process: regulated exocytosis; synaptic vesicle membrane organization
Cellular component: extracellular exosome; cytoplasmic vesicle membrane; membrane; neuromuscular junction; synaptic vesicle membrane; lipid droplet; synaptic vesicle
Genetic constraint (gnomAD): Loss-of-function variants: 14 observed, 20.43 expected, observed/expected ratio (o/e) 0.69, 90% interval 0.45 to 1.07. The upper end of that interval is the gene's LOEUF score, 1.07, which puts it in group 4 of 6, group 1 being the genes least tolerant of losing a copy. Missense variants: 246 observed, 275.77 expected, observed/expected ratio (o/e) 0.89, 90% interval 0.8 to 0.99. Synonymous variants: 124 observed, 120.32 expected, observed/expected ratio (o/e) 1.03, 90% interval 0.89 to 1.2.
Homologues: Orthologues: macaque SYNGR2 (97% identical), dog SYNGR2 (90% identical), mouse Syngr2 (89% identical), rat Syngr2 (88% identical), guinea pig SYNGR2 (81% identical), pig SYNGR2 (78% identical), zebrafish syngr2b (50% identical), Caenorhabditis elegans sng-1 (29% identical). Paralogues in human: SYNGR1 (50% identical), SYNGR3 (46% identical), SYNGR4 (34% identical).
Diseases named in the same sentence as SYNGR2 in open-access papers:
SYNGR2 is named in the same sentence as 13 diseases in open-access papers, as found by Europe PMC text mining. Sharing a sentence is not in itself a finding about the gene and the disease. The quoted sentences say what the papers report.
Bunyavirus infection (2 papers, 2017 to 2020). "SYNGR2 also reportedly promotes Bunyavirus infection via interaction with viral non-structural proteins and other studies implicate SYNGR2 in intracellular vesicular protein transport." (PMID 32686835, 2020).
COVID-19 (1 paper, 2024). A disease caused by infection with severe acute respiratory syndrome coronavirus 2. "Noteworthy, in a recent study on the upper airway host transcriptional response of patients with COVID-19 to other viral lung infections SYNGR2 was found to be upregulated >1.035-fold and 1.35-fold when compared with nonviral respiratory disorders." (PMID 38698905, 2024).
esophageal cancer (1 paper, 2023). A primary or metastatic malignant neoplasm involving the esophagus. "Previous studies have found that the expression of SYNGR2 in esophageal cancer is related to immune cell infiltration." (PMID 37170221, 2023).
hepatocellular carcinoma (1 paper, 2025). A malignant tumor that arises from hepatocytes. "Increased abundance of ARRB1, as well as FBXO11, LYZ, RPS6KB1, and SYNGR2 have comparable oncogenic effects in hepatocellular carcinoma, and MGST1 and RPS6KB1 have noted oncogenic roles in various lung cancers." (PMID 40186098, 2025).
Obesity (1 paper, 2026). Accumulation of substantial excess body fat. "Lastly, our study identifies several differently regulated proteins whose role in obesity and adipose tissue is poorly known, such as ANXA8, DDX39B, STX7, SYNCRIP, SYNGR2, and PAK2." (PMID 41077621, 2026).
Thrombocytopenia (1 paper, 2018). A reduction in the number of circulating thrombocytes. "Recently, SYNGR2 was implicated as an active player in promoting viral RNA replication and immune evasion of severe fever with thrombocytopenia syndrome virus (SFTSV), a novel tick-borne bunyavirus in humans." (PMID 30379811, 2018).
thyroid nodule (1 paper, 2012). A small circumscribed mass in the THYROID GLAND that can be of neoplastic growth or non-neoplastic abnormality. "A 10-gene (KIT, SYNGR2, C21orf4, Hs.296031, Hs.24183, FAM13A1, C11orf8, KIAA1128, IMPACT, CDH1) and a 6-gene (KIT, LSM7, SYNGR2, C21orf4, Hs.296031, Hs.24183) assays have been proposed to have high diagnostic accuracy to distinguish thyroid nodules." (PMID 22958914, 2012).
viral infections (1 paper, 2023). "Synaptogyrin-2 (SYNGR2) is a transmembrane protein implicated in promoting bacterial and viral infections." (PMID 38011217, 2023).
infection (2 papers, 2018 to 2023). The state of being infected such as from the introduction of a foreign agent such as serum, vaccine, antigenic substance or organism. "Infection of a CRISPR-Cas9 mediated SYNGR2 knock-out porcine kidney 15 (PK15) cell line significantly reduced PCV2b replication beginning 24 hours post infection." (PMID 38011217, 2023). "In vitro infection of a predicted SYNGR2 knock-out edited PK15 clone with the same PCV2b isolate demonstrated clear involvement of SYNGR2 in viral replication." (PMID 38011217, 2023). "Specifically, we found a mutation in the SYNGR2 gene that influences the ability of the PCV2 virus to replicate, which can affect pig growth and immune system following infection." (PMID 30379811, 2018). "Therefore, a function of SYNGR2 predominantly in the early stages of PCV2b infection is a logical conjecture." (PMID 38011217, 2023). "While further analysis is necessary to understand the exact functional mechanism, the lag in PCV2 replication during the first 24 hours post infection in edited clones compared to wildtype cells, highlights a potential function of SYNGR2 in the early stages of PCV2 infection." (PMID 38011217, 2023). "In vitro silencing of SYNGR2 resulted in a decrease in viral replication and a reduction in the number and size of the inclusion bodies, further substantiating the role of SYNGR2 in facilitating SFTSV infection." (PMID 30379811, 2018). "In our research we did not observe an increase in SYNGR2 mRNA levels following in vitro or in vivo infection with PCV2." (PMID 30379811, 2018). "A reduction in viral titer was observed in the SYNGR2 silenced cells subjected to PCV2b starting at 48 hours post infection (hpi) when compared to scramble siRNA and non-transfected control cells, indicating a role of SYNGR2 in viral replication (P < 0.05)." (PMID 30379811, 2018).
tumor (2 papers, 2023 to 2024). "Furtherly, we used receiver operating characteristic (ROC) curve to assess the diagnostic Value of SYNGR2 expression levels between tumor and normal tissues." (PMID 37170221, 2023). "We examined the expression patterns, prognostic values, and diagnostic value of SYNGR2 in pan-cancer, and investigated the relationship of SYNGR2 expression with tumor mutation burden (TMB), microsatellite instability (MSI), immune infiltration, and immune checkpoint (ICP) genes." (PMID 37170221, 2023). "Moreover, this study totally explored the potential association of SYNGR2 with clinical characteristics, tumor mutation burden (TMB), microsatellite instability (MSI), immune infiltration, and immune checkpoint genes." (PMID 37170221, 2023). "Moreover, SYNGR2 is differentially expressed in a variety of tumors and aberrant expression is associated with the progression of the tumor, especially in LIHC." (PMID 37170221, 2023). "Synaptogyrin-2 and Gal-3 abundances decreased in superficial tumor regions as the budding index increased." (PMID 39195201, 2024). "Results showed that SYNGR2 expression was positively related to TMB in BLCA, STAD, PRAD, and other tumor tissues; while negatively associated with TMB in SARC, and CESC." (PMID 37170221, 2023). "In paired samples, the expression of SYNGR2 in tumor tissues of BLCA, BRCA, CHOL, and others are significantly higher than the corresponding control tissues." (PMID 37170221, 2023). "Results indicated that SYNGR2 was significantly associated with immune cell subsets in BRCA, GBM, HNSC, and other tumor tissues." (PMID 37170221, 2023). "The expression of SYNGR2 in tumor tissue is higher than that in non-tumor tissue (p < 0.001), and the SYNGR2high group had a worse OS compared with the SYNGR2low group in K-M curve (p < 0.05)." (PMID 37170221, 2023). "We investigated the clinical relevance of SYNGR2 in the different tumor types using Kaplan–Meier survival analysis regarding OS, DSS, DFI, and PFI." (PMID 37170221, 2023). "Moreover, the synaptogyrin-2 abundance in the tumor surface showed a decreasing trend significantly correlated with the worsening of the Dukes stage and budding index." (PMID 39195201, 2024). "SYNGR2 participates in the carcinogenic progression, and may contribute to the immune infiltration in tumor microenvironment." (PMID 37170221, 2023). "Furthermore, SYNGR2 expression levels increased with tumor progression in THCA, SKCM, PAAD, and other tumor tissues." (PMID 37170221, 2023). "Taking into account the lack of normal samples in the TCGA database for some cancer types, we integrated the GTEx database for further analysis and the results showed that the expression level of SYNGR2 in most tumor tissues are much higher than the corresponding control tissues." (PMID 37170221, 2023). "The AUC values suggested that SYNGR2 could reliably distinguish tumor from normal tissues for various types of cancer, especially THCA (AUC = 0.87), PRAD (AUC = 0.85), LIHC (AUC = 0.92), KIRP (AUC = 0.89), KICH (AUC = 0.99), ESCA (AUC = 0.85), BRCA (AUC = 0.90), and UCEC (AUC = 0.85)." (PMID 37170221, 2023). "A pan-cancer analysis revealed that compared to normal tissues, significantly elevated mRNA expression levels of SYNGR2 were observed in 26 cancers, including BLCA, BRCA, CESC, and other tumor tissues." (PMID 37170221, 2023). "The correlation test indicated that SYNGR2 was extensively correlated to immune cell infiltrates in BRCA, GBM, HNSC, and other tumor tissues." (PMID 37170221, 2023). "The results revealed that SYNGR2 mRNA level was significantly higher expressed in BLCA, BRCA, CHOL, LIHC, and other tumor tissues in comparison to corresponding normal tissues." (PMID 37170221, 2023). "In terms of MSI, the SYNGR2 expression was positively related to MSI in DLBC, ESCA, KIRC, LIHC, and THCA; while negatively related to MSI in COAD, LUSC, OV, and other tumor tissues." (PMID 37170221, 2023).
tumor (continued). "SYNGR2 expression was found to positively correlate with the immune score in STAD, UVM, UCEC, and other tumor tissues, but negatively correlated with the immune score in PRAD." (PMID 37170221, 2023). "Our pan-cancer analysis revealed that SYNGR2 expression was positively related to TMB in BLCA, STAD, PRAD, and other tumor tissues." (PMID 37170221, 2023). "Notably, among the less-abundant proteins in S vs. H and D vs. H comparisons, eight were never detected in S, and one, synaptogyrin-2, was never detected in D tumor samples." (PMID 39195201, 2024).
cancer (1 paper, 2023). A tumor composed of atypical neoplastic, often pleomorphic cells that invade other tissues. "Our study suggests that SYNGR2 can serve as a predictor related to prognosis in pan-cancer, especially LIHC." (PMID 37170221, 2023). "In order to investigate the application of SYNGR2 in cancer prognosis, we built a nomogram for predicting the OS, DSS, PFI of LIHC patients." (PMID 37170221, 2023). "Meanwhile, we also evaluated the prognostic value of SYNGR2 in pan-cancer based on multiple databases." (PMID 37170221, 2023). "Our exploration demonstrated that SYNGR2 is positively correlated with immune scores in most cancer types." (PMID 37170221, 2023). "Univariate Cox regression analysis showed that high expression of SYNGR2 significantly reduces the OS in 6 types of cancers including KIRC, KIRP, LGG, LIHC, SARC, and UCEC." (PMID 37170221, 2023). "Synaptogyrin-2 (SYNGR2), as a member of synaptogyrin gene family, is overexpressed in several types of cancer." (PMID 37170221, 2023). "To date, the evidence of SYNGR2’s implications in cancer is very preliminary and lacks experimental validation." (PMID 37170221, 2023). "In the present study, we explored the pan-cancer expression profiles of SYNGR2, and the correlation between SYNGR2 aberrant expression and patient prognosis in different cancers." (PMID 37170221, 2023). "Collectively, SYNGR2’s potential roles in carcinogenesis and cancer development are worthwhile to be further disclosed." (PMID 37170221, 2023). "In this study, we examined the expression of SYNGR2 across 33 cancer types." (PMID 37170221, 2023). "Overall, SYNGR2 expression was significantly upregulated in various cancers." (PMID 37170221, 2023). "The RNA expression of SYNGR2 in pan-cancer data was first evaluated using the TCGA database." (PMID 37170221, 2023). "The current study indicates that SYNGR2 has promise as a prognostic biomarker in various cancers." (PMID 37170221, 2023). "In addition, we also found that aberrant SYNGR2 expression was correlated with increased immune cell infiltration of T regulatory cells (Tregs) in the majority of cancers." (PMID 37170221, 2023). "Our findings demonstrated that SYNGR2 could be a potential biomarker, as well as a predictor of survival and immunotherapy in cancer treatment." (PMID 37170221, 2023). "However, the role of SYNGR2 in pan-cancer is largely unexplored." (PMID 37170221, 2023). "The high expression of SYNGR2 significantly reduced the overall survival (OS), disease-specific survival (DSS), disease-free interval (DFI), and progression-free interval (PFI) in multiple types of cancer." (PMID 37170221, 2023). "However, the effects of enhanced SYNGR2 gene expression on prognosis have not been systematically evaluated across different cancer types." (PMID 37170221, 2023).
SYNGR2 also shares sentences with these, for which no sentence is quoted: lung carcinoma (1 paper); respiratory disorders (1).